IL6 (interleukin 6)
Diseases named in the same sentence as IL6 in open-access papers (continued):
Sharing a sentence is not in itself a finding about the gene and the disease.
influenza (continued). "Pro-inflammatory cytokines, including TNF-α, interleukin (IL)-1β, and IL-6 have been implicated in the loss of appetite and weight in influenza infection, chronic inflammatory disorders and cancer." (PMID 22536437, 2012). "In contrast, in the case of high-dose influenza, smoke exposure was associated with heightened IL-6 and TNFα responses." (PMID 20920950, 2011). "Plasma levels of IL-6 have been reported to associate with the severity of the disease also in influenza and Japanese encephalitis." (PMID 20500875, 2010). "Moreover, immunocompromised individuals, particularly the elderly, are prone to elevated risk of severe influenza, largely driven by IL-6-mediated hyperinflammation." (PMID 40692679, 2025). "Decreased phagocytic activity has been observed in both singular influenza infection and singular aspergillus infection in IL‐6 deficient mice and how IL‐6 signaling affects effector function during IAPA is an area that warrants additional investigation in the future." (PMID 40420617, 2025). "We hypothesize that the increased IFNγ levels seen in IL‐6 deficient mice during IAPA may be driven by influenza infection." (PMID 40420617, 2025). "Numerous studies involving both humans and animals indicate that humoral responses to HA and NA, along with viral load and innate inflammatory markers - particularly IL-6, IL-8, and neutrophil indices - are consistently linked to the clinical severity of influenza and RSV." (PMID 41583233, 2025). "However, IL‐6 has been shown to be protective during influenza infection, with IL‐6 deficient mice having increased morbidity and mortality." (PMID 40420617, 2025). "IL‐6 may be protective during influenza infection; however, excessive levels of IL‐6 may cause cytokine storm and lung injury." (PMID 39921246, 2025). "Given the poor survival observed in IL‐6 deficient mice during influenza and post‐influenza streptococcal pneumonia and the hypothetical use of IL‐6 antagonists during influenza infection, we sought to determine the role of IL‐6 inhibition during post‐influenza MRSA pneumonia." (PMID 39921246, 2025). "The results suggest that elevated levels of IL-4, IL-6, and IL-10, which are associated with Th2 cell activation, might be related to severe influenza, but the increased TNFα and IFNγ levels also need to be paid attention." (PMID 40558593, 2025). "Through an in silico study, we identified IL-6 as a hub target associated with influenza infection." (PMID 39000173, 2024). "In this study, CRP ≥ 7.57 mg/L, IL-6 ≥ 9.84 pg/ml, Days from onset of Flu symptoms to hospitalization ≤4.5 days, CSF-TP ≥ 194.8 mg/L, and FluA were found to be independent risk factors for severe influenza combined with febrile seizures." (PMID 39507495, 2024). "Using mice deficient in specific DC subsets, IL-6, or neutrophils, in combination with influenza and SARS-CoV-2 challenge models, here we show that the mRNA-LNP platform can support protective immune responses in the absence of specific DC subsets, IL-6 and neutrophils." (PMID 35073387, 2022). "Prevention of platelet aggregation using other compounds has also been shown to improve survival in mouse models of severe influenza and is associated with reduced inflammation, reduction in proinflammatory cytokine levels (IL-1β, IL-6, TNF-α, and MIP-2) and reduced platelet activation." (PMID 33499234, 2021). "Finally, in a murine acute lung injury and ARDS model, MC-derived IL-6 induces apoptosis in lung-infiltrating neutrophils, which are also known to contribute to influenza-associated inflammation and immune pathology." (PMID 33680987, 2021). "Influenza promotes hypoxia that induces a pro-inflammatory state in the endothelium, causing the increased release of IL-1, IL-6, platelet-activating factor, intercellular adhesion molecule (ICAM)-1, p-selectin, and von Willebrand factor, all of which are associated with platelet activation." (PMID 33562193, 2021).
influenza (continued). "Moreover, TNF-α (top) and IL-6 (bottom) mRNA expression in unstimulated B cells are negatively associated with the in vivo influenza vaccine response (B) and with the in vitro AID mRNA expression (C)." (PMID 32180773, 2020). "Importantly, IL-6 has been shown to contribute to T cell responses in influenza infection, and mice deficient in IL-6 show reduced T cell numbers in the lung and LLNs." (PMID 33373420, 2020). "Patients with influenza-associated acute encephalopathy/encephalitis exhibited neurological symptoms like seizure, altered arousal, and abnormal behaviors, which were associated with increased concentrations of IL-1β, IL-6, and TNF-α in serum and CSF." (PMID 32850927, 2020). "IL-6 plays an important role in B-cell maturation, is closely associated with antibody production during infections and vaccination, and positively regulates the anti-influenza B-cell responses." (PMID 33244316, 2020). "In addition, elevated IL-6 during influenza infection has been associated with haemophagocytic syndrome resulting increased lung damage and worse outcome." (PMID 32038632, 2019). "This study was able to show that IL-6 is crucial for cell death and macrophage phagocytosis enhancing resistance to superinfected S. pneumoniae, resulting in decreased susceptibility to secondary S. pneumoniae infection after primary influenza infection." (PMID 32038632, 2019). "In influenza infection, mice deficient in IL-6 had decreased survival and more severe lung injury." (PMID 28262742, 2017). "This dysregulation of TNF-α and IL-6 vs. IL-10 response to influenza vaccination has been linked to the downregulation of the expression of the costimulatory molecules CD80 and CD86 by activated monocytes as a predictor of the antibody response to influenza vaccination." (PMID 28769922, 2017). "In support of this hypothesis, heightened early production of inflammation-associated cytokines including IL-6 is associated with the fatal outcome of influenza H7N9 infection, consistent with a role for inflammation in driving influenza-associated diseases." (PMID 28240600, 2017). "In addition, the induction of AQP4 expression and edema formation has been well studied in animals with influenza-associated encephalopathy induced by proinflammatory cytokines, including IL-1, IL-6 and TNF-α in cultured astrocytes." (PMID 29216295, 2017). "Furthermore, macrophage recruitment to the lung and phagocytic activities of macrophages during influenza infection were reduced in IL-6-deficient mice." (PMID 28262742, 2017). "By extension, our data imply that inadequate AM, TGF-β, and/or IL-6 responses may contribute to the development of ALI following infection by highly pathogenic influenza strains." (PMID 25840995, 2015). "Although some specific cytokine profiles such as high Th1, low Th2, high IL-6, and low Th17 cytokines may serve as reliable indicators and independent risk factors for intermittent positive pressure ventilation in patients with influenza infection." (PMID 38898404, 2024). "Interestingly, our group has previously shown in humans that CD11bhi-expressing monocytes are highly proinflammatory (production of TNF-α and IL-6 following LPS stimulation) compared with CD11blo, and they negatively associate with influenza vaccine–induced antibody titers in HIV+ individuals." (PMID 34491910, 2021). "Thus, it is possible that the lower efficacy of our inactive influenza viral vaccine in the IL-6 deficient mice could be due to impaired memory CD4/CD8 T cell response and the subsequent antibody response." (PMID 33193346, 2020). "In addition, IL-6 has been identified as the main cause of fever in influenza infection." (PMID 22808082, 2012). "Influenza infection increased IL-6, IL-8, IL-10, and CXCL-10 secretion, consistent with previous reports." (PMID 40929365, 2026).
influenza (continued). "One of the earliest immune responses to influenza infection is to produce pro-inflammatory cytokines such as IL-6 and TNF-α alongside interferons such as IFN-α and IFN-β, which facilitate the recruitment of immune cells to defeat the infection." (PMID 41602762, 2026). "In severe influenza infections, IL-6, along with other cytokines like TNF-α and IL-1β, can exacerbate the disease, leading to complications such as ARDS." (PMID 40692679, 2025). "Increased level of IL-6, IL-1β, TNFα, and IFN-β in response to influenza can damage the placenta and cause intrauterine fetal growth impairments." (PMID 41567998, 2025). "After 6 and 12 months after vaccination against influenza, the IL-6 level in all groups was within the normal range, but its significant reduction compared to the baseline values was observed after 12 months." (PMID 39937802, 2025). "Inflammatory cytokines such as TNF-α and IL-6, released post-influenza infection, can further enhance bacterial adhesion and invasion." (PMID 40572089, 2025). "The current evidence supports the anti-influenza and anti-inflammatory properties of alkaloids, but their relationship with inflammatory mediators such as IL-6 and TNF-α needs further clarification." (PMID 40076449, 2025). "Studies using IL-6 knockout models suggest that IL-6 boosts both innate and adaptive immune responses to influenza." (PMID 40692679, 2025). "In influenza and staphylococcal sepsis, cytokines such as IL-6 and TNF-α promote tissue factor expression and suppress anticoagulant pathways (e.g., protein C, antithrombin), leading to microthrombi and consumption of clotting factors." (PMID 40564724, 2025). "There is a body of evidence that suggests that IL-6 is critical in the transition from innate to adaptive immunity in the response to influenza infection, albeit in animal models." (PMID 40561994, 2025). "In children with influenza, a higher level of circulating IL-6 is correlated with greater disease severity." (PMID 40263387, 2025). "Following viral clearance and clinical recovery, 1 month post-influenza, mice demonstrate increased protection from S. pneumoniae due to Mo-AMs producing elevated levels of IL-6." (PMID 40748050, 2025). "BCG vaccination influences the increase in TNF-α and IL-6 production following influenza vaccination." (PMID 40718526, 2025). "BCG vaccination influences the increase in TNF-α and IL-6 production induced by the influenza vaccination." (PMID 40718526, 2025). "IL-6 has been shown as a potential biomarker for assessing influenza severity, with elevated levels correlating with disease progression and poor clinical outcomes." (PMID 40692679, 2025). "Prior studies have thoroughly investigated IL‐6 signaling in both singular influenza and singular aspergillus infections in the lung and observed beneficial effects of IL‐6 in these models." (PMID 40420617, 2025). "The strong association between IL-6 and disease severity has spurred interest in targeting IL-6 or it signaling pathways, highlighting its dual role as both a biomarker and a therapeutic target in influenza and other inflammatory conditions." (PMID 40692679, 2025). "An imbalanced cytokine response, marked by excessive IL-6, correlates with severe disease outcomes in influenza." (PMID 40692679, 2025). "Twelve months after vaccination against influenza, the study participants had significantly lower IL-6 levels, and COPD patients, additionally, showed a reduction in IL-10 levels compared to baseline." (PMID 39937802, 2025). "This pattern mirrors observations in severe seasonal influenza, where ferrets exhibited reduced interferon induction and heightened IL-6 levels." (PMID 40692679, 2025). "In severe influenza infections, elevated IL-6 levels correlate with increased disease severity, lung inflammation, and poor clinical outcomes." (PMID 40692679, 2025).
influenza (continued). "Targeting IL-6 signaling pathway is an important alternative therapeutic strategy for mitigating hyperinflammation in severe influenza cases." (PMID 40692679, 2025). "Paradoxically, studies have shown that early upregulation of SOCS3 (a negative regulator of IL-6/STAT3 signaling) occurs independently of IL-6 during influenza infection." (PMID 40248710, 2025). "We evaluated serum concentrations of seven cytokines (IL-2, IL-4, IL-6, IL-10, TNFα, IFNγ, and IL-17a) as potential biomarkers for influenza severity in pregnant women." (PMID 40558593, 2025). "In severe influenza cases, the observed Th2-polarized cytokine profile (marked by elevated IL-4, IL-6, and IL-10 levels) is consistent with established pregnancy-associated immune modulation." (PMID 40558593, 2025). "Multiple lines of evidence support that IL-6 protects the host against influenza by enhancing antiviral responses." (PMID 40692679, 2025). "IL‐6 KO mice have a similar inflammatory cytokine profile to WT mice during post‐influenza MRSA pneumonia, including GM‐CSF, RANTES, TNFα, IFNγ, and IL‐4." (PMID 39921246, 2025). "Higher TNFα and IL-6 levels in influenza patients have been shown to correlate with severe disease or fatal outcome." (PMID 40333697, 2025). "Although key players in the inflammatory response, interleukin-6 (Il6.c) and interleukin-1b (Il1b) also have protective effects after influenza infection and show reduced up-regulation in obese lungs compared to control." (PMID 38728395, 2024). "It was reported that significantly higher levels of IL-1β and IL-6 were detected in influenza patients with more severe conditions." (PMID 39000173, 2024). "The TOLL receptor pathway, which triggers inflammatory damage during viral cytopathogenesis, is often thought to be highly associated with increased influenza morbidity and significant changes in TNF-α, IL-6 and iNOS during Toll receptor pathway activation." (PMID 38426086, 2024). "The cytokine storm involving IFN-α, C–C chemokine motif ligand 2, IL-6, and TNF, is often associated with mortality related to influenza and heightens the risk of AKI and neuroinflammation." (PMID 39676169, 2024). "This device has been employed in various POCT applications, including for quantification of interleukin-6 (IL-6) levels in serum to assess the severity of influenza infections in children." (PMID 39771085, 2024). "For example, elderberries were found to show potent anti-influenza activity by affecting the post-infection phase and viral transmission and by modulating the release of the cytokines, interleukin-6 (IL-6), IL-8, and tumor necrosis factor (TNF)." (PMID 38998923, 2024). "The level of IL-6 was 26.14 ± 7.20 pg/mL for influenza and 32.60 ± 3.68 pg/mL for coronavirus infection (rate 0.68 ± 0.04; p > 0.05)." (PMID 39344895, 2024). "Interleukin 6, one of the prominent inflammatory cytokines, is essential for viral control in influenza infection." (PMID 38400083, 2024). "In this study, the mice that were infected with influenza and were orally administered the mixed probiotics showed significant reductions in IL-6 and TNF-α levels, suggesting a potential alleviation of influenza-induced inflammatory storms." (PMID 39410114, 2024). "Studies have shown that IL-6 levels increase significantly after Flu infection and are correlated with the severity of febrile seizures and brain damage in children." (PMID 39507495, 2024). "The secretion of inflammatory cytokines such as TNF-α, IL-1β, and IL-6 post influenza infection also promotes bacterial adhesion and invasion." (PMID 39065060, 2024). "IL-6 levels were reported to be significantly increased in the sera of patients with uncomplicated influenza." (PMID 39000173, 2024). "As expected, CXCL10 and IFNα levels were highest in influenza infection, whereas IL6, IL10, IL1β, and PROK2 (which is highly inducible in macrophages by LPS and other TLR2/4 agonists) reached higher levels in the bacterial infections." (PMID 39395995, 2024).
influenza (continued). "A study found that IL-6 is crucial for mice survival after infection with influenza through the optimization of T cell regulation and the migration and phagocytic activities of macrophages." (PMID 37238072, 2023). "The gene ATP6vd02 is induced in response to IL-6, and TGF-beta is known to upregulate IL-6, which aids in tissue repair and reduced influenza induced immunopathology." (PMID 38322710, 2023). "Ginsenoside Rb1 boosted IgG and antibody subtypes in the H1N1 influenza vaccine, improved survival of mice after virus challenge, attenuated lung histopathological damage, and reduced inflammatory cytokines expression in IL-6 and TNF-α." (PMID 37868069, 2023). "During inflammation, influenza vaccination leads to reduced levels of proinflammatory cytokine (IL-6, IL-8 and TNF-α) and an increase in IL-10 levels." (PMID 37766096, 2023). "Striking reactivities were observed particularly for IFN-α8, IFN-γ, IL-6, IL-7, IL-12p70, and IL-22, while serum from 1 patient with influenza showed high MFI levels for both GM-CSF and soluble RANK ligand." (PMID 36752204, 2023). "Within 1 month of influenza infection, MO-AMs are transcriptionally similar to monocytes and produce more interleukin-6 (IL-6) upon stimulation." (PMID 37779697, 2023). "The present study found in vitro treatment of PBMCs with MMEs elevated IL-6 in the presence of both influenza and rhinovirus." (PMID 37432355, 2023). "In an RCT of patients with influenza, combination therapy with oseltamivir and azithromycin showed significant improvement in the levels of inflammatory cytokines, such as IL-6, CXCL8/IL-8, IL-17, CXCL9/MIG, sTNFR-1, and IL-18." (PMID 37243228, 2023). "The superinfected lungs had significantly elevated levels of IL-6, TNFα, and IFNβ during the early stages of influenza infection, but their levels dropped if the fungal challenge occurred at later stages of influenza infection." (PMID 37681974, 2023). "In response to influenza viral entry, epithelial cells induce proinflammatory cytokines and chemokines such as IL-1β, IL-6, TNFα, CCL2, CCL3, and CCL5, which recruit macrophages and neutrophils to the site of infection to help control the virus." (PMID 38112660, 2023). "Interleukin‐6 (IL‐6), monocyte chemoattractant protein‐1 (MCP‐1) and tumor necrosis factor (TNF) are pro‐inflammatory cytokines commonly associated with influenza‐induced cytokine storms." (PMID 36969366, 2023). "Accordingly, IL-6−/− mice experience worse disease severity after influenza compared to wild-type mice." (PMID 35912114, 2022). "Infection with influenza leads to the activation of inflammatory cells and an increase in pro-inflammatory cytokines such as IL-1, IL-6, and TNF-α." (PMID 36560418, 2022). "Two identified cytokines, IL-6 and IL-10, were shown to be significantly elevated in mice administered CAF09b after influenza infection." (PMID 35163772, 2022). "In the setting of influenza, IL-6 has been shown to mediate phagocytic activity in macrophages, increase fibroblast apoptosis, and improve epithelial survival, thus promoting viral clearance while maintaining the epithelium and minimizing fibrosis." (PMID 35912114, 2022). "Lung homogenates were evaluated by multiplex ELISA (Quansys) to quantify several cytokines (TNFα, IFNγ, IL-1α, IL-1β and IL-6) and chemokines (MCP-1, MIP-1α and RANTES) implicated in influenza-mediated acute lung injury 33,34." (PMID 35410323, 2022). "For example, Lianhuaqingwen Capsule (LH-C) has proven effective against influenza and reduced the pro-inflammatory cytokines (IL-6 and TNF-α) in the lungs of mice." (PMID 35123452, 2022). "Consistent with the results of our previous experiments, LS inhibited the expression of inflammatory factors such as TNF-α、IL-6、IL-1α、IFN-γ after influenza infection in vivo and in vitro." (PMID 36034844, 2022). "Studies showed that IL-6 also enhanced virus clearance and the immune cell response during influenza infection." (PMID 34696461, 2021).